IGF2 (insulin like growth factor 2)
Diseases named in the same sentence as IGF2 in open-access papers (continued):
Sharing a sentence is not in itself a finding about the gene and the disease.
cognitive decline (9 papers, 2021 to 2025). "The downregulation of Igf2 in the young treated group might be implicated in their observed cognitive decline, contrasting the beneficial treatment effect seen in old mice, regardless of sex." (PMID 37534036, 2023). "Our data suggests that, in a scenario of continuous erosion of synaptic mTOR activity, acute injection with IGF2 is the treatment of choice to postpone cognitive decline." (PMID 39192595, 2024). "In order to further validate the influence of Akt/mTOR/IGF2 downregulation on the cognitive decline phenotype, we investigated if IGF2 injection can rescue memory consolidation in aged Tsc2+/− mice." (PMID 39192595, 2024). "The neurotrophic peptide insulin‐like growth factor‐2 (IGF2) is a promising candidate for both treating and preventing AD‐induced cognitive decline." (PMID 36971212, 2023). "Modified MSCs also reduced cognitive decline, boosted Aβ clearance, and attenuated microglia activation as well as neuronal cell apoptosis by upregulation of the insulin-like growth factor 2 (IGF2)-elicited signaling axis." (PMID 35842587, 2022). "IGF2 has also been found to rescue age‐related cognitive decline in rats." (PMID 36971212, 2023). "In cognitively normal subjects, or those with moderate levels of cognitive decline, IGF2 may be administered alongside a cognitively stimulating activity such as crossword puzzle or video game." (PMID 36971212, 2023). "Therefore, should middle-aged cortical astrocytes of WMI express lower levels of Igf2 in addition to the whole hippocampus, they could contribute to the premature cognitive decline present in the WMIs." (PMID 38338968, 2024).
embryonal tumors (9 papers, 2010 to 2025). "It is generally accepted that loss of imprinting (LOI) at the IGF2/H19 locus results in biallelic expression of the fetal growth factor IGF2 and contributes to the development of embryonal tumors." (PMID 23825673, 2013). "Overexpression of the insulin-like growth factor 2 (IGF2) has been reported as a common characteristic in both WT and other embryonal tumors." (PMID 23825673, 2013). "Both loci were chosen due to the known overexpression of IGF2 and NNAT in embryonal tumors and their key role in embryonic development." (PMID 23825673, 2013). "Thus, the occurrence of embryonal tumors in early life is a major concern in patients with BWS and ICR1/IGF2 alterations." (PMID 25943194, 2015).
endometriosis (9 papers, 2013 to 2026). The growth of functional endometrial tissue in anatomic sites outside the uterine body. "Validation in gestational epithelial endometriosis organoids showed upregulation of IGF2 and NR2F2, and downregulation of LIF." (PMID 42282918, 2026). "Immunohistochemistry was used to assess PRL-R and GH hormones, as well as IGF1 and IGF2 expressions, in normal endometrium and endometriosis tissues." (PMID 40076699, 2025). "IGF1 and IGF2 showed significantly higher expression in both epithelium and stroma of controls compared to endometriosis samples." (PMID 40076699, 2025). "Another study showed a decrease in IGF2 expression levels in eutopic and ectopic endometriosis endometrial cells compared to controls." (PMID 38791310, 2024). "It was noted that the expression profiles of the H19, IGF1 and IGF2 genes werereduced in eutopic and ectopic endometrial tissues of patients with endometriosis compared to control tissues." (PMID 38791310, 2024). "The work of scientists from Iran has shown that the expression of the VEGF, IGF1, IGF2 and H19 lncRNA genes and the epigenetic changes of H19 lncRNA play a dynamic role in the pathogenesis of endometriosis." (PMID 38791310, 2024). "The results showed that expression of H19, IGF1 and IGF2 genes was decreased in eutopic and ectopic endometrial tissues of endometriosis group in comparison with control group." (PMID 35459174, 2022). "Our results showed that women with endometriosis had decreased IGF1 expression as well as decrease in the level of IGF2 expression in the eutopic and ectopic endometrium of endometriosis group compared to the controls." (PMID 35459174, 2022). "In the present study, we evaluated and compared expression levels of H19 RNA factor and angiogenic (VEGF) and proliferative (IGF1, IGF2) genes in endometrium of non-endometriosis women in comparison with eutopic and ectopic tissues of endometriosis women." (PMID 35459174, 2022). "Genes expression profile of H19, IGF1 and IGF2 was decreased in eutopic and ectopic endometrial tissues of endometriosis group, compared to the control tissues." (PMID 35459174, 2022). "Findings of this study showed that VEGF, IGF1, IGF2 and H19 lncRNA genes expression and epigenetic alterations of H19 lncRNA have dynamic role in the pathogenesis of endometriosis." (PMID 35459174, 2022). "IGF1 and IGF2 play roles in cell proliferation and differentiation, suggesting dysregulation of these processes may occur in endometriosis." (PMID 39198675, 2024). "Additionally, hypomethylation of H19-DMR region II may be involved in impaired IGF2 regulation in endometriosis." (PMID 35459174, 2022). "Similarly, in JAR cells co-cultured with gestational epithelial endometriosis, NR2F2 and IGF2 were upregulated, whereas MDFI, SP3, and RDH10 were downregulated." (PMID 42282918, 2026). "Decreased H19 expression in endometriosis lesions probably decreased IGF1 and IGF2 expression." (PMID 35459174, 2022). "The present study was designed to elucidate VEGF, IGF1, IGF2 and H19 lncRNA genes expression and epigenetic alterations of differentially methylated region (DMR) of H19 (H19-DMR) regulatory region in endometrial tissues of patients with endometriosis, in comparison with control women." (PMID 35459174, 2022). "To determine whether reduced IGF2 and H19 gene expressions in endometriosis was because of epigenetic modifications or not, we then analyzed epigenetic alterations of the H19-DMR regulatory regions." (PMID 35459174, 2022). "In this case–control study, 24 women with and without endometriosis were studied for the relative expression of VEGF, IGF1, IGF2 and H19 lncRNA genes using real-time polymerase chain reaction (PCR) technique." (PMID 35459174, 2022).
Hypertension (9 papers, 2013 to 2025). The presence of chronic increased pressure in the systemic arterial system. "At the beginning of hypertension, the expression of IGF-2 is induced under pathological state, increasing the miR-483-3p level in endothelial cells." (PMID 35222797, 2022).
leiomyosarcoma (9 papers, 1997 to 2025). An uncommon, aggressive malignant smooth muscle neoplasm, usually occurring in post-menopausal women. "For example, IGF2 signals through IR-A in the leiomyosarcoma cell line SKUT1, which induces an autocrine feedback loop that enhances cell growth." (PMID 29758070, 2018).
lung adenocarcinoma (9 papers, 2009 to 2024). A carcinoma that arises from the lung and is characterized by the presence of malignant glandular epithelial cells. "Since a previous study concerning IGF2 LOI in lung adenocarcinoma refers to histological type, the association between the histological grade of the adenocarcinoma sample and LOI was also analyzed in the present study." (PMID 25364428, 2014). "CTC counts correlated to tumor progression in patients with early lung adenocarcinoma and successfully detected typical mutant genes (Notch1, IGF2, EGFR, and PTCH1) and genes in smokers as predictive biomarkers." (PMID 37371825, 2023). "In the present study, IGF2 LOI was detected in approximately half of adenocarcinomas but not in any of the squamous cell carcinomas examined; thus, IGF2 LOI may be a marker of lung adenocarcinoma." (PMID 25364428, 2014). "Furthermore, scRNA-Seq analysis revealed that IGF2 was mainly expressed in CAFs but not in other cell populations within mammary EO771 tumors and various human cancers, including BRCA, COAD, and lung adenocarcinoma (LUAD)." (PMID 39545420, 2024).
Stroke (9 papers, 2010 to 2026). Sudden impairment of blood flow to a part of the brain due to occlusion or rupture of an artery to the brain. "Also, IGF1 and IGF2 levels have been found to associate inversely with ischemic stroke risk in a Danish case-control study, and also with stroke outcome in human studies." (PMID 24373343, 2013). "The administration of Atr I, Atr III, and Pae has shown significant enhancements in long-term stroke recovery in mice, likely due to the promotion of angiogenesis via increased activation of the IGF-2 pathway in ischemic brain tissue." (PMID 38178130, 2024). "Also, it is interesting that four of the eleven top-ranked proteins for association with stroke risk are members of the IGF signaling pathway (IGFBP4, IGF2, IGFBP6, IGFBP2)." (PMID 20667078, 2010).
cholangiocarcinoma (8 papers, 2003 to 2023). A carcinoma that arises from the intrahepatic biliary tree (intrahepatic cholangiocarcinoma) or from the junction, or adjacent to the junction, of the right and left hepatic ducts (hilar cholangiocarcinoma). "Elevated focal IGF-2 transcript levels may therefore indicate an increased risk for hepatocellular and cholangiocellular carcinomas." (PMID 12618883, 2003). "The IGF2/IGF1R/IR axis mediates adaptive resistance to erlotinib by undergoing an IGF1R/IR phenotypic switch in cholangiocarcinoma." (PMID 34831014, 2021). "In cholangiocarcinoma (CCA), the interaction between cancer cells and CAFs mediated by insulin-like growth factor 2 (IGF2), insulin receptor (IR) and IGF1 receptor (IGF1R) was found to regulate ERL resistance." (PMID 30927928, 2019).
fibrous tumors (8 papers, 2017 to 2025). "The most common tumours associated with IGF‐2‐mediated hypoglycaemia were fibrous tumours (N = 124, 53.2%), followed by non‐fibrous tumours originating from the liver (N = 21, 9%), hemangiopericytoma (N = 20, 8.5%) and mesothelium (N = 11, 4.7%)." (PMID 38411039, 2024). "A systemic review of IGF-2-mediated NICTH included 233 patients and found fibrous tumors to be the most common underlying malignancy (53.2%)." (PMID 41209155, 2025).
liver diseases (8 papers, 2010 to 2026). "In particular, recently, many studies have evaluated the correlation between increased levels of IGF1 receptors and liver diseases and the oncogenic role of IGF2 and its involvement in angiogenesis, migration and, consequently, in tumour progression." (PMID 25225571, 2014). "In addition, the IGF-2/ERK signaling pathway enhances hepatic stem cell proliferation and self-renewal in patients with portal hypertension, and specific knockout of IGF-2 results in intestinal stem cell growth inhibition." (PMID 36358907, 2022). "In addition, IGF-2 has been identified as a potential biomarker in liver diseases." (PMID 36358907, 2022).
memory impairment (8 papers, 2014 to 2024). "We compiled recent studies on the role of IGF2 in AD-associated memory issues and summarized the current knowledge regarding IGF2 expression and function in the brain, specifically in AD-induced memory impairment." (PMID 39830039, 2024). "The theoretical way IGF-2 deficiency disrupts healthy conditions would be through memory impairment and by altering cognitive processes." (PMID 36076984, 2022). "One of the arguments for using this route is that in Fmr1-/- mice (an animal model of Fragile X syndrome), learning and memory impairments were ameliorated by intranasal IGF-2." (PMID 33673334, 2021). "In this study, we examined the effect of recombinant IGF-2 on memory impairment due to intracerebral hemorrhage (ICH)." (PMID 34466449, 2018). "However, the use of IGF2 as a potential target for the development of novel pharmaceuticals to treat AD-induced memory impairment needs further investigation." (PMID 39830039, 2024). "The expression of Igf2 has been shown to repair stress-induced memory impairments in young rats." (PMID 36263297, 2022). "Moreover, the effect of IGF-2 on memory impairment in pathologic conditions and brain damage is still unknown." (PMID 34466449, 2018). "In this study, we observed that recombinant IGF-2 could significantly increase avoidance memory, but did not have a significant effect on recognition memory impairment caused by ICH." (PMID 34466449, 2018). "Another study revealed that neonatal administration of thyroxine and metformin in patients with FASD improved memory impairment via elevating DNMT1 and consequently normalizing hippocampal deiodinase-III (Dio3) and insulin-like growth factor 2 (Igf2) expressions in the adult offspring." (PMID 37373281, 2023). "Hence, our results contribute to the body of evidence accumulated in recent years that IGF2 plays an important role in learning and memory formation, and demonstrate that by restoring dendritic spine density, IGF2 may significantly promote the recovery of memory impairments." (PMID 25100745, 2014).
overgrowth syndrome (8 papers, 2014 to 2025). A group of syndromes caused by genetic birth defects that may lead to the development of malignancies. "From the study of overgrowth syndrome-associated WT, germline dysregulation was identified in the imprinted region at 11p15 affecting imprinted genes IGF2 and H19." (PMID 25478630, 2014). "Loss of imprinting of IGF2 results in excessive production of this fetal growth factor, an event which has been identified in nearly 70% of WT and is associated with the overgrowth syndromes, Beckwith-Wiedemann and hemihypertrophy, that are well known to predispose to WT." (PMID 24481423, 2014). "Indeed, both cumulative and recent findings display a more diversified landscape of IGF2 regulation, extending beyond the previously known abnormalities linked to either (a) epigenetic deregulation or (b) allelic (uniparental) disomy, both of which are described in IGF2 overgrowth syndromes." (PMID 37371750, 2023). "For instance, the genetic alteration of the IGF-2 gene locus playing the driving role in overgrowth syndromes and WT was less frequently seen in children with WT from Japan in comparison to Caucasian children." (PMID 35911825, 2022). "Interestingly, a study conducted on an overgrowth syndrome characterized by NSD1 deficiency, a molecular defect found in a subset of BWS, demonstrated the role of NSD1 as a specific co-activator for a novel enhancer in DMR0 affecting IGF2-p0 transcriptional activity in a cell-type-specific manner." (PMID 37371750, 2023).
cardiac hypertrophy (7 papers, 2018 to 2025). "The module also includes the genes IGF1 and IGF2 that are involved in the differentiation of immature cardiomyocytes and have been associated with cardiac hypertrophy." (PMID 30405693, 2018). "Those co-expressed genes including some important coding genes (Srf, Akt, Igf2, etc.)which have been reported to be involved in the pathogenesis of cardiac hypertrophy." (PMID 35402096, 2022). "Cardiac hypertrophy in neonatal LOI mice is mediated by circulating IGF2 activation of AKT/mTOR signaling in cardiomyocytes and is independent of H19 gene function." (PMID 34402430, 2021). "Another interesting new finding was that m6A modification enhanced the recruitment of miR-133a-RISC (RNA-induced silencing complexes)-AGO2 (Argonaute 2-Insulin-like growth factor 2) to its targets in heart development and in response to cardiac hypertrophy and proliferation." (PMID 35858921, 2022). "In addition, IGF-2/IGF-2R induces pathological cardiac hypertrophy through the calcium/calmodulin-dependent protein kinase II (CaMKIIδ) and calcineurin signaling pathways, which can be alleviated by combining inhibitors of CaMKIIδ and calcineurin." (PMID 36358907, 2022). "In addition to rodents, patients with BWS characterized by IGF-2 overexpression also develop cardiomyopathy characterized by myocardial hypertrophy and myocardial fibrosis as pathological features." (PMID 36358907, 2022). "Additionally, on average, hiPSC-CM lacking HO-1 were 13.4% (±4.8%) bigger than hiPSC-CM WT; this observation is also supported by increased expression of IGF2, a key factor involved in cardiac hypertrophy." (PMID 33804563, 2021).
growth disorders (7 papers, 2013 to 2023). "In humans, maternal blood IGF2 methylation was associated with birth weight and IGF2 expression in the placenta was associated with fetal growth disorders." (PMID 37810933, 2023). "A humanized mouse line carrying a mutation of the H19/IGF2 imprinting control region demonstrates how tissue-specific and mosaic imprinting alterations result in growth disorders with opposite clinical pictures and asymmetric growth of bilateral organs." (PMID 29470501, 2018). "Insulin-like growth factors 1 and 2 (IGF-1 and IGF-2) are important biomarkers in research and diagnosis of growth disorders." (PMID 33569646, 2021).
hemangioma (7 papers, 2013 to 2025). A benign vascular lesion characterized by the formation of capillary-sized or cavernous vascular channels. "Furthermore, Beckwith-Wiedmann Syndrome (BWS), where hemangiomas are considered a supportive finding of the diagnosis—is associated with duplications or a loss of imprinting of the IGF2/H19 locus that leads to IGF2 overproduction." (PMID 26496499, 2015). "IGF1 drives both proliferation and adipocyte differentiation of hemangioma stem cells, while IGF2 elevated in proliferative IH, promotes HemSC growth and adipogenesis via upregulation of PPARγ-CEBP axis." (PMID 40978048, 2025). "Other genes known to be expressed in hemangioma such as IGF-2 and GLUT-1 are also expressed in response to hypoxia." (PMID 39997620, 2025). "The distinct behaviors of IGF1 (showing increased m6A modification but decreased expression during involution) and IGF2 (exhibiting coordinated reduction in both m6A levels and expression) highlight critical aspects of m6A biology in hemangioma progression." (PMID 40978048, 2025). "IGF2 is known to stimulate angiogenesis in vitro, and increased IGF2 mRNA expression was found in vascular tufts in the retina of mice in the oxygen-induced retinopathy model and in human vascular tumors such as hemangiomas." (PMID 29951828, 2018). "Involuted hemangiomas expressed the lowest levels of IGF2, approximately 6X lower than their proliferating counterparts (p = 0.01)." (PMID 26496499, 2015). "Previous studies have confirmed elevated expression of HIF1A, IGF1, and IGF2 in hemangioma tissues." (PMID 40978048, 2025). "Moreover, explant hemangioma cultures grow strongly in response to exogenous IGF2." (PMID 26496499, 2015).
Huntington disease (7 papers, 2020 to 2025). Huntington disease (HD) is a rare neurodegenerative disorder of the central nervous system characterized by unwanted choreatic movements, behavioral and psychiatric disturbances and dementia. "Consistent with a role in Aβ clearance, IGF2 has been shown to reduce non‐amyloid extracellular protein aggregates in a mouse model of Huntington's disease." (PMID 36971212, 2023). "IGF-2 was also shown to reduce the accumulation of intracellular polyglutamine proteins in Neuro2a cells and of mutant huntingtin in neuronal cultures derived from Huntington’s disease (HD) patients." (PMID 33673334, 2021).
leiomyoma (7 papers, 1997 to 2024). A well-circumscribed benign smooth muscle neoplasm characterized by the presence of spindle cells with cigar-shaped nuclei, interlacing fascicles, and a whorled pattern. "For this reason, IGF2 might be associated with the development of leiomyomas." (PMID 29891843, 2018). "The IGF2 mRNA upregulation (≥ 10-fold) was observed only in usual leiomyoma." (PMID 37466765, 2024). "In addition, the up-regulation of IGF2 and SMemb mRNA expression was detected in leiomyomas treated with GnRHa." (PMID 29891843, 2018).